STAT3 (signal transducer and activator of transcription 3)
Diseases named in the same sentence as STAT3 in open-access papers (continued):
Sharing a sentence is not in itself a finding about the gene and the disease.
tumor (continued). "Positive expression of p-Stat3 was found in 10 (83.3%) tumours of distant recurrence and 5 (83.3%) tumours of local recurrence." (PMID 19638983, 2009). "Avicins dephosphorylate Stat3 in a variety of human tumor cell lines, leading to a decrease in the transcriptional activity of Stat3." (PMID 19440292, 2009). "Caffeic acid is a known suppressor of tumor angiogenesis that acts in human retinal carcinoma cells by blocking STAT3-mediated VEGF expression." (PMID 19917137, 2009). "Accumulating evidence suggests that constitutively activated STAT3 contributes to tumor development and progression in numerous forms of cancer including those of the breast, head and neck, prostate, skin, ovary, lung, bone, and blood." (PMID 19284568, 2009). "Pretreatment of the cells was necessary in order to avoid JAK2/STAT3 inhibition in the tumor cells while focusing on signaling events within the APC." (PMID 19718269, 2009). "STAT3 has been recently proposed as an important molecule that mediates tumor induced immunosupression." (PMID 19718269, 2009). "Collectively, tumor cells were shown to secrete soluble factors that activate STAT3 and suppress DCs function." (PMID 19718269, 2009). "Here we show that in addition to releasing soluble factors, tumor cells, physically interact with APCs, consequently inducing the activation of STAT3." (PMID 19718269, 2009). "STAT3 is known to regulate the expression of many downstream targets important in tumor growth and survival such as survivin and VEGF through its binding to specific sequences in promoter regions of these target genes." (PMID 19284568, 2009). "Tumors were shown to secrete a variety of tumor-derived factors that activate STAT3 within infiltrating APCs." (PMID 19718269, 2009). "In support of this, a variety of inhibitors of STAT3 have been shown to inhibit tumor cell growth and induce apoptosis both in vitro and in vivo." (PMID 19284568, 2009). "We did not observe a correlation by Spearman correlation between the degree of p-STAT-3 levels in the tumor and the percent of PBMCs displaying p-STAT-3." (PMID 19900287, 2009). "Inhibiting STAT3 in tumor cells resulted in increased production of pro-inflammatory factors and reversed DC suppressive effects." (PMID 19519895, 2009). "Recently, several inhibitors against Stat3 activation have been established that showed the induction of apoptosis or cell-cycle arrest in cancer cells, or decreased tumour volumes in vivo." (PMID 19638983, 2009). "STAT3 is constitutively active in many tumor cells and was found to have an important role in oncogenesis." (PMID 19718269, 2009). "It has been found that STAT3 participates in carcinogenesis, and that the ectopic expression of a constitutively active form of STAT3 (STAT3-C) induces tumor formation in nude mice." (PMID 19730699, 2009). "The signal transducer and activator of transcription 3 is an oncogenic protein that is capable of inducing tumours and enhancing cancer proliferation." (PMID 19127268, 2009). "Overall, p-STAT-3 regulates immune suppression and tumor progression via multiple redundant mechanisms." (PMID 19900287, 2009). "STAT3 activation has also been implicated in angiogenesis: STAT3 is a direct transcription activator of the VEGF gene and activation of STAT3 leads to tumor-associated angiogenesis in vivo." (PMID 19519895, 2009). "Recent studies have suggested that tumor cells secrete tumor-derived factors that induce STAT3 activity within neighboring APCs, effecting their maturation and function." (PMID 19718269, 2009). "Although tyrosine kinase receptors, such as EGFR, are capable of activating STAT3, the incidence of STAT3 activation by inflammatory cytokines (such IL-6) in cooperation with EGFR is common among some tumours." (PMID 19088723, 2009). "Enhancer of Zeste Homolg 2 (EZH2) expression is regulated by RUNX1, STAT3 and E2F3 and high expression of EZH2 gene is associated with the tumor death and also correlated to the pathological stage." (PMID 20025723, 2009).
tumor (continued). "Constitutively activated STAT3 correlates with a more malignant tumor phenotype, resistance to chemotherapeutics, and is associated with decreased survival in some cancers." (PMID 19284568, 2009). "We further assessed the contribution of soluble and contact-dependent factors to the increase in STAT3 activation in tumor cell-APC co-cultures." (PMID 19718269, 2009). "In contrast to Stat3, Stat1 is anti-oncogenic; it is a potent inhibitor of tumor growth and promoter of apoptosis." (PMID 19274102, 2009). "Consistent with a role of Stat3/5 in oncogene-addiction, phosphorylation of Stat3/5 has been shown to diminish in tumor cells undergoing apoptosis upon oncogene inactivation in vitro." (PMID 18461184, 2008). "Constitutive activation of STAT3 has been reported to be sufficient to induce tumor formation in a range of human cancers." (PMID 18939993, 2008). "Interference of constitutive Stat3 signaling pathway suppresses chemotherapy resistance, tumor growth and metastasis, induces cancer cell death and therefore shows great potential for cancer therapy." (PMID 18939995, 2008). "HDI was found to up-regulate pSTAT1, whereas it down-regulates pSTAT3 and total STAT3 levels in both tumor cells and lymphocytes." (PMID 18954464, 2008). "Activation of STAT3 can lead to cell-cycle progression, anti-apoptotic effects, proangiogenesis, immune evasion, and tumor invasion and metastasis." (PMID 18939993, 2008). "STAT3 plays a critical role in the oncogenesis of several malignancies and has been shown to be activated in tumour tissue and in normal mucosa of HNSCC patients." (PMID 18234094, 2008). "Our laboratory is examining the effects of paracrine signaling from breast cancer cells and breast fibroblasts with increased phosphorylated STAT3 (p-STAT3) levels on tumor progression." (PMID 18939993, 2008). "The level of bcl-xl and cyclin D1 was lower in STAT3 decoy ODN-treated tumor-bearing mice compared with that in vehicle control or scramble control (p < 0.05)." (PMID 17683579, 2007). "Inhibition of STAT3 signalling resulted in the decreased survivin and c-myc expression in many tumor cell lines, however, in A549 cells, the transcription levels of survivin and c-myc were not down-regulated by STAT3 decoy ODN treatment." (PMID 17683579, 2007). "Since cyclin D1 and bcl-xl are thought to be the downstream proteins of activated STAT3, which greatly contributes to tumor progression, we then examined the expression levels of these two proteins by western blot." (PMID 17683579, 2007). "Though there are multiple oncogenic signaling pathways in each individual tumor, blockade of STAT3 signaling is often sufficient to induce growth arrest and apoptosis in many different tumors." (PMID 17683579, 2007). "Stat3 has been classified as a proto-oncogene because an activated form of Stat3 can mediate oncogenic transformation in cultured cells and tumour formation in nude mice." (PMID 17311011, 2007). "Compared to PBS vehicle control and scramble control, STAT3 decoy ODN significantly inhibited the tumor growth in mice as well as remarkably increased the number of TUNEL-positive apoptotic cells in xenograft tumor tissues." (PMID 17683579, 2007). "Stat3 is classified as a proto-oncogene, because an activated form of Stat3 can mediate oncogenic transformation in cultured cells and tumour formation in nude mice." (PMID 17311011, 2007). "Activation of Stat3 has been detected in many human neoplasias, and it has been shown that IL-6-type cytokines induce Stat3 phosphorylation in various human and rodent cell lines." (PMID 17925034, 2007). "The number of TUNEL positive cells in tumor tissues treated with STAT3 decoy ODN was significantly greater than that treated with vehicle or scramble ODN." (PMID 17683579, 2007).
tumor (continued). "Constitutive Stat3 signaling appears to play a role in the cell transformation and tumour progression by stimulating cell growth, promoting tumour angiogenesis, mediating immune evasion and conferring resistance to apoptosis induced by chemotherapeutic agents." (PMID 17311011, 2007). "This study investigates both the expression levels and activation of the IL-6R/JAK/STAT3 pathway in matched hormone-sensitive and hormone-refractory tumours from the same patient." (PMID 17595657, 2007). "Immunohistochemistry using IL-6R, JAK1, STAT3, pSTAT3Tyr705 and pSTAT3Ser727 antibodies was performed on 50 matched hormone-sensitive and hormone-refractory tumours pairs." (PMID 17595657, 2007). "First, sensitivities of image analysis methods were compared in the IHC staining of phosphorylated signal transduction and transcription factor-3 (p-STAT3) in tumor xenografts." (PMID 17326824, 2007). "In a variety of human cancers, constitutive activation of Stat3 is sufficient to induce tumour formation." (PMID 17311011, 2007). "Herein, we report that STAT3 signalling downstream from EGFR autocrine activation leads to increase tumour cell motility and invasiveness." (PMID 16804520, 2006). "Both antisense oligonucleotides and siRNA directed against STAT3 limited tumour cell transmigration to below the levels noted in the absence of added EGF." (PMID 16804520, 2006). "Epigenetic events, in addition to transcriptome changes signalled through STAT3, also contribute to tumour cell motility and invasion." (PMID 16804520, 2006). "Among the candidate genes regulated by STAT3 in this regard are matrix metalloproteinase-2, which is essential for tumor invasion and metastasis formation." (PMID 15647107, 2005). "Blocking STAT3 in tumor cells induces the expression of pro-inflammatory cytokines and chemokines that activate innate immunity and dendritic cells." (PMID 16001973, 2005). "In various tumour cell lines, persistent signalling of specific STATs, in particular STAT3 and STAT5, has been shown to stimulate cell proliferation and prevent apoptosis through upregulating a number of target genes, such as c-Myc, cyclins and bcl-x." (PMID 12865928, 2003). "Constitutive activation of Stat3 plays an important role in the tumorigenesis of various types of human cancer, and abrogation of Stat3 signalling has been correlated with stimulation of cell proliferation, prevention of apoptosis and tumour formation." (PMID 12454768, 2002). "Blockade of P2X7R by AZ10606120 appears to activate a pro-tumor IL-6/STAT3 axis." (PMID 41896344, 2026). "Nuclear STAT3 then drives expression of genes that support tumour cell proliferation and survival." (PMID 41531453, 2026). "Additionally, the analysis of postoperative relapse cases revealed sustained STAT3 activation in residual tumor cells following surgical intervention." (PMID 41560805, 2026). "Moreover, CD8+ T cells depletion abrogates the therapeutic benefits of RAGE/Stat3 inhibition by restoring the tumor growth in S100A7 overexpression mice." (PMID 42057180, 2026). "The overexpression of ITM2B1‐115 resulted in elevated p‐STAT3 levels in tumor tissues; again, this increase could be abolished by TSPAN4 knockdown." (PMID 41319268, 2026). "NET-CCDC25 interaction promotes tumor cell chemoresistance via STAT3 activation and EMT." (PMID 41480760, 2026). "Having demonstrated that inhibition of STAT3 not only directly inhibits tumor growth and invasion but also reduces astrocytes' ability to promote tumor growth, this treatment strategy is highly attractive for targeting both tumor cells and their microenvironment." (PMID 41560805, 2026). "Moreover, our study also shed light on the dynamic interplay between the S100A7/RAGE/Stat3 signaling pathway and immune cell infiltration within the tumor microenvironment." (PMID 42057180, 2026). "Our findings reveal that tumor M-MDSCs upregulate 6PGD expression via IL-6/STAT3 signaling." (PMID 41535266, 2026).
tumor (continued). "Moreover, H2 treatment decreases STAT3 phosphorylation and Bcl-2 expression in various organs and tumor models." (PMID 41596287, 2026). "The hyperactivation of STAT3 in these TME cells may exert a significant impact on the anti-tumor immune response through multiple mechanisms." (PMID 41560805, 2026). "This review synthesizes mechanistic evidence showing how JAK/STAT signaling, predominantly through STAT1 and STAT3, integrates inflammatory cues, oncogenic stress, and microenvironmental signals to regulate PD-L1 expression across tumor cells and immune compartments." (PMID 41858895, 2026). "These autophagosomes are subsequently delivered to macrophages via extracellular vesicle (EVs) and then triggers autophagic cell death and p62-guided STAT3 destruction within the macrophages, thereby eliminating M2 TAMs and reprograming the tumor immune microenvironment." (PMID 41731604, 2026). "Moreover, MND-ART-GEL downregulated STAT3 expression, thereby suppressing tumor cell invasion and migration." (PMID 41998636, 2026). "We hypothesize that IL-6/GP130/JAK/STAT3 pathway activation is comparable between tumor tissue and adjacent stromal tissue." (PMID 41397158, 2025). "In ovarian cancer, an intraperitoneal, thermosensitive hydrogel reservoir provides sustained release of STAT3-siRNA polyplexes, enriches nodules, and significantly delays tumor growth in advanced models, aligning with reviews positioning PNPs to overcome systemic instability and chemoresistance." (PMID 41304838, 2025). "In addition, IL-6 promotes STAT3 activation in Tumor Cells, thereby enhancing their resistance to apoptosis and increasing their proliferation rate." (PMID 41333481, 2025). "Similarly, RES suppresses STAT3 signaling, inhibiting tumor growth, angiogenesis, and epithelial‐mesenchymal transition in NSCLC models." (PMID 40860906, 2025). "Collectively, these observations suggest that CT features reflecting tumor aggressiveness may serve as imaging surrogates of miR-10a-5p/TFR1/STAT3/CD24 dysregulation." (PMID 41551164, 2025). "Furthermore, IL-6 promotes the expression of the anti-apoptotic protein Bcl-2 through STAT3 signaling, enabling tumor cells to evade chemotherapy-induced cytotoxicity." (PMID 40563367, 2025). "Notably, maslinic acid further suppresses the IL-6/JAK/STAT3 signaling cascade, regulates autophagy, and inhibits angiogenesis by impairing the formation of new blood vessels that support tumor growth." (PMID 40872208, 2025). "Targeted inhibition of signal transducer and activator of transcription 3 (STAT3) may play an anti-cancer role by improving the tumor immune microenvironment and changing the metabolism of cancer cells." (PMID 40309242, 2025). "For instance, phosphosite‐resolved signalling may distinguish immune‐inflamed versus stromal/mesenchymal‐dominant states, or separate tumours with STAT3/TGF‐β–driven EMT from those dominated by ECM remodelling and macrophage programs." (PMID 41292185, 2025). "Dysregulated PTMs—including phosphorylation, acetylation, ubiquitination, and glycosylation—alter key signaling pathways (e.g., NF-κB, STAT3, Wnt/β-catenin), metabolic reprogramming, and interactions with the tumor microenvironment, enabling MM cells to evade therapies such as PIs and IMiDs." (PMID 40427595, 2025). "Notably, in follicular thyroid carcinoma, EphA5 reportedly promotes tumor cell proliferation and suppresses apoptosis via activation of the STAT3 signaling pathway, implicating it in tumor progression and a poor prognosis." (PMID 40806980, 2025). "Therefore, the presented strategy introduces an innovative approach for regulating “undruggable” targets in tumor cells, providing a therapeutic strategy for treatment of STAT3-regulated cancers." (PMID 40118821, 2025). "To test this hypothesis, we introduced the STAT3 phosphorylation inhibitor Stattic into SLC9A2-knockdown tumor cells and observed that the upregulation of VEGFA induced by SLC9A2 knockdown was reversed." (PMID 40474298, 2025).
tumor (continued). "In addition, the nuclear translocation dimer PKM2 (in a low activity state) acts as a protein kinase and transcriptional coactivator to activate STAT3 signaling pathway in tumor cells." (PMID 40948745, 2025). "TREM1 highly expressed in myeloid cells, maintains the tumor inflammatory microenvironment via the NF-κB/IL-6/STAT3 pathway; it may also directly activate pro-survival signals within tumor cells (e.g., PI3K-AKT)." (PMID 41415031, 2025). "Specifically, five cancers demonstrated higher STAT3 expression in tumor tissues." (PMID 40265014, 2025). "Thus, our results suggested that MCPIP1 reduced hybrid EMT and tumor stemness in PC cells by inhibiting the IL6/JAK2/STAT3 signaling axis." (PMID 40874680, 2025). "Furthermore, in HCC, M2 macrophages have been shown to contribute to tumor progression via the IL-6/STAT3 signaling pathway." (PMID 39652104, 2025). "MAZ promotes tumor-associated angiogenesis by controlling genes like VEGF; its repression can be induced by factors such as oxidative stress and epigenetic changes, sustaining tumor growth and blood supply through pathways like STAT3 signaling." (PMID 41155227, 2025). "Our observation that miR-10a-5p overexpression leads to reduced STAT3 phosphorylation suggests that this microRNA may exert its tumor-suppressive effects, at least in part, through the modulation of STAT3 signaling." (PMID 41551164, 2025). "Tumor analysis revealed decreased levels of phosphorylated STAT3." (PMID 41148817, 2025). "In BC cells, the signaling pathways TNFα/NFκB and IL6/STAT3 are known to promote tumor progression via activation of key EMT-related transcription factors, such as Snail Family Transcriptional Repressor 1 (Snail1), Twist-related protein 1 (Twist1), and Zinc finger E-box binding homeobox 1 (ZEB1)." (PMID 40807456, 2025). "Dysbiosis compromises epithelial barrier integrity and facilitates the translocation of bacterial components such as LPSs, which activate Pattern Recognition Receptor (PRR)-dependent NF-κB and STAT3 signaling, thereby promoting chronic inflammation, tumor survival, angiogenesis, and metastasis." (PMID 41463196, 2025). "Pacritinib and Fedratinib, both JAK2-selective inhibitors that display efficacy in myeloproliferative disorders, are being investigated for their relevance in solid tumors like BC and have shown promising results in reducing STAT3 activity and tumor progression in TNBC models." (PMID 41463071, 2025). "Once activated, STAT3 primarily promotes tumor cell growth, metastasis, and immune evasion." (PMID 39907159, 2025). "In HCC, activation of the IL‐6/STAT3 pathway directly enhances the expression of TIMP‐1 in liver cancer cells, converting normal hepatic fibroblasts to cancer‐associated fibroblasts, thus altering the tumour microenvironment and promoting tumourigenesis." (PMID 39778006, 2025). "Thus, inhibition of this pathway disrupts the signaling and recruitment of immunosuppressive myeloid-derived cells and downstream activation of the Signal Transducer and Activator of Transcription 3 (STAT3) pathway leads to tumor cell proliferation." (PMID 40427130, 2025). "In this issue of the JCI, Sun, Zhang, and colleagues identified nonhistone ENSA-K63 lactylation as a critical regulator that inactivates PP2A, activates STAT3/CCL2 signaling, recruits tumor-associated macrophages (TAMs), and suppresses cytotoxic T cell activity." (PMID 40166931, 2025). "Functionally, MAML1 promoted tumor malignancy by regulating STAT3 activity." (PMID 41345959, 2025). "FABP4 may exert its tumour-suppressive effects by downregulating Snail and phosphorylated STAT3 (p-STAT3), inhibiting the epithelial-mesenchymal transition (EMT) and oncogenic STAT3 signalling." (PMID 41149452, 2025).